EIF4E (eukaryotic translation initiation factor 4E)
Diseases named in the same sentence as EIF4E in open-access papers (continued):
Sharing a sentence is not in itself a finding about the gene and the disease.
asthma (5 papers, 2012 to 2025). "We have earlier reported that an impaired translation-initiation of the CEBPA mRNA in BSM cells of asthma patients was associated with the decreased expression of the translation regulator eIF4E." (PMID 22500186, 2012). "An existing study demonstrated that EIF4E knockdown inhibits the extensive proliferation and migration of airway smooth muscle cells induced by platelet-derived growth factor BB in asthma." (PMID 34654440, 2021). "Recently, eIF4E has been reported to be required for ASMC hypertrophy in asthma, and inhibiting the phosphorylation of eIF4E may present a new therapeutic option to limit inflammation and remodeling in asthmatic airways." (PMID 31695627, 2019).
autism spectrum disorder (5 papers, 2019 to 2024). A spectrum of developmental disorders that includes autism, and Asperger syndrome. "While EIF4E overexpression was reported to induce autism spectrum disorders (ASD) like behavior deficits, depression-like behavior and cognitive impairment., the mechanisms are not fully explored." (PMID 39557567, 2024). "This manuscript offers a novel and intriguing exploration of the mechanisms linking eIF4E overexpression to autism spectrum disorder (ASD)-like behaviors, particularly through microglial activation and reduced oxytocin levels." (PMID 39557567, 2024). "Specifically, rpS6, p-eIF4E, TSC1 and p-MNK1 expression discriminated patients according to their clinical diagnosis, suggesting that components of protein synthesis signalling pathways might constitute a molecular signature of clinical severity in autism spectrum disorder." (PMID 30705255, 2019).
cardiac hypertrophy (5 papers, 2020 to 2023). "In line with its role in cellular growth control, increased eIF4E expression and phosphorylation are associated with progression of cardiac hypertrophy." (PMID 32164190, 2020). "A major finding in our study is that testosterone-mediated changes in the expression level of myocardial mTOR/S6K1/4EBP1/eIF4E signaling pathway play a critical role in the pathogenesis and development of cardiac hypertrophy in SHR after ovariectomy." (PMID 34874016, 2022). "In mouse models with TAC, pressure overload activated phosphorylation of ribosomal S6 protein and eukaryotic translation initiation factor-4E (eIF4E), which were suppressed by RP, suggesting a critical role of S6K in mediating cardiac hypertrophy." (PMID 33513917, 2021). "Testosterone-induced ovariectomy SHR cardiac hypertrophy may be related to the expression of mTORC1/S6K1/4EBP1/eIF4E." (PMID 34874016, 2022). "Thus, levels of eIF4E are important for regulating normal cell growth, and its dysregulation is observed to play a role in both cardiac hypertrophy and cancer, where increased protein synthesis is required." (PMID 32164190, 2020). "Therefore, this study provides evidence that mTOR/S6K1/4EBP1/eIF4E signaling pathway may be necessary for the mechanism of the Testosterone-induced OVX SHR myocardial hypertrophy response." (PMID 34874016, 2022). "As expected, it was observed that PI3K, AKT, GSK3β, mTOR, P70S6K, and eIF-4E were significantly phosphorylated in the TAC group, suggesting that PI3K-Akt signaling pathway was indeed activated in cardiac hypertrophy." (PMID 33778070, 2021). "It was observed that PI3K, AKT, GSK3β, mTOR, P70S6K, and eIF-4E were significantly phosphorylated in TAC mice, suggesting that PI3K-Akt signaling pathway was indeed activated in cardiac hypertrophy." (PMID 33778070, 2021). "In cardiac hypertrophy, the PI3K-Akt signaling pathway is activated by many types of cellular stimuli or toxic insults to regulate fundamental cellular processes including protein synthesis, proliferation, and survival, via its downstream signals, such as AKT, GSK3β, mTOR, P70S6K, and eIF-4E." (PMID 36704572, 2023).
Cognitive impairment (5 papers, 2017 to 2026). Abnormal cognition is characterized by deficits in thinking, reasoning, or remembering. "Considering our finding that overexpression of eIF4E led to decreased oxytocin expression levels, we hypothesize that the social cognitive impairment observed in these mice may be associated with neuroinflammation resulting from reduced oxytocin expression." (PMID 39557567, 2024). "Depressive-like behavior was improved by inhibition of eIF4E phosphorylation and GABA receptor activation, whereas cognitive impairment was only improved by inhibition of eIF4E phosphorylation." (PMID 41680149, 2026). "The present study suggests that overexpression of eIF4E may induce hyperactivation of microglia and contribute to social cognitive impairment by decreasing oxytocin levels in the hippocampus." (PMID 39557567, 2024).
diffuse large B-cell lymphoma (5 papers, 2014 to 2019). "Moreover, 77% (110/142) of diffuse large B cell lymphoma tumors expressed eIF4E and this was associated with an inferior event free survival." (PMID 25839159, 2015).
osteosarcoma (5 papers, 2018 to 2025). A usually aggressive malignant bone-forming mesenchymal neoplasm, predominantly affecting adolescents and young adults. "As the presence of VPg decreased the translation of capped mRNA in wheat germ extracts and human osteosarcoma cancer cells, VPg was suggested to sequester eIF4E away from host mRNA translation." (PMID 37983287, 2023). "Analysis of cytoplasmic extracts by co-immunoprecipitation studies from vehicle- and NP-treated osteosarcoma cells show that NP increased the binding of 4E-BP1 to eIF4E at 16 h in 143B and MG63 cells, respectively." (PMID 30286779, 2018). "To determine whether NP regulates protein synthesis block at the level of initiation, we investigated the regulation of eIF4E and eIF4E-binding protein 1 (4E-BP1) in osteosarcoma cells." (PMID 30286779, 2018). "Thus, given the apparent role of the eIF4E pathway in malignant transformation, it is possible that NP-induced STAT3-dependent control of osteosarcoma cell functions could, in part, work through the regulation of protein synthesis." (PMID 30286779, 2018). "Western blot analysis revealed that NP does not affect the levels of eIF4E and control protein GAPDH, though it does modulate 4E-BP1 protein levels in osteosarcoma cells at the level of phosphorylation." (PMID 30286779, 2018).
triple-negative breast carcinoma (5 papers, 2014 to 2024). An invasive breast carcinoma which is negative for expression of estrogen receptor (ER), progesterone receptor (PR), and human epidermal growth factor receptor 2 (HER2). "In the present study, we have demonstrated that eIF4E induced cisplatin-resistance in ESCC mainly by promoting PI3K/AKT pathway and increasing Bcl-2/Bax ratio, which is similar to eIF4E in triple-negative breast cancer cells." (PMID 27588477, 2016). "Targeting Mnk/eIF4E pathway for blocking Mnk function and eIF4E phosphorylation is therefore a novel approach for treating BCs, particularly for Her2-positive and triple negative breast cancers that have no indications for endocrine therapy or effective treatment regimes." (PMID 24504069, 2014).
calicivirus infection (4 papers, 2015 to 2024). "Calicivirus infections lead to the shut-off of cellular translation that is associated with changes in the translation apparatus, including cleavage of the poly(A) binding protein PABP, dissociation of eIF3 from eIF4G, and phosphorylation of eIF4E." (PMID 39339889, 2024). "This prompted us to investigate how calicivirus infection may influence eIF4E activity." (PMID 25561727, 2015).
esophageal cancer (4 papers, 2009 to 2021). A primary or metastatic malignant neoplasm involving the esophagus. "We also found that eIF4E knockdown significantly potentiated cisplatin - induced cytotoxicity and long-term cell growth suppression, hence sensitizing esophageal cancer cells to cisplatin treatment in vitro and in vivo." (PMID 27588477, 2016). "In esophageal cancers, there are more BP1-eIF4E complexes than in normal tissues, further complicating the accepted model of BP1 regulation of eIF4E." (PMID 20049173, 2009).
mesothelioma (4 papers, 2009 to 2017). A usually malignant and aggressive neoplasm of the mesothelium which is often associated with exposure to asbestos. "It has to be established with future work if a causative relation between c-myc expression and eIF4E exists in mesothelioma cells." (PMID 22216185, 2011). "When mesothelioma cells are transfected with 4EASO there is an expected decrease in eIF4E protein levels, demonstrated with immunoblot analysis, and concordant decrease in cell viability when compared to mmASO." (PMID 28968974, 2017). "The three mesothelioma cell lines exhibited extensive decreases in eIF4E protein levels that appeared to be dose dependent." (PMID 24260583, 2013). "In light of the findings that selectively reducing eIF4E levels substantially enhances mesothelioma cell killing by either pemetrexed or gemcitabine support the clinical evaluation of 4EASO combined with chemotherapy." (PMID 24260583, 2013). "Mesothelioma cells were transfected with 4EASO, designed to target eIF4E mRNA, or mismatch-ASO control." (PMID 24260583, 2013). "4EASO treatment resulted in dose dependent decrease in eIF4E levels, which corresponded to cytotoxicity of mesothelioma cells." (PMID 24260583, 2013). "In this study, 4EASO that specifically targets eIF4E mRNA for destruction is assessed as a therapeutic agent against mesothelioma." (PMID 24260583, 2013). "In this study, disabling the eIF4F complex by targeting eIF4E with eIF4E-specific antisense oligonucleotide (4EASO) is assessed as a therapy for mesothelioma." (PMID 24260583, 2013). "In order to explore the possibility that suppression of eIF4E levels by 4EASO treatment would lead to apoptotic cell death in mesothelioma, poly (ADP-ribose) polymerase cleavage was investigated following 4EASO treatment." (PMID 24260583, 2013). "Consistent with the activation of the cap-mediated translation complex, the quantity of eIF4E-bound eIF4G was increased in most mesothelioma cell lines treated with IGF-I for 20 or 300 min compared with that in untreated cells." (PMID 19603014, 2009). "For each mesothelioma cell line stably transfected with empty vector, eIF4G avidly bound to eIF4E, which is indicative of a translationally active state." (PMID 19603014, 2009). "Further, if repressing cap-mediated translation by reducing eIF4E levels attenuates measles virus cytotoxicity, then forcing mesothelioma cells to produce an endogenous repressor protein of eIF4E, 4E-BP1, should also result in a similar decreased sensitivity to measles virus oncolysis." (PMID 28968974, 2017). "Evidence is presented establishing that suppression of eIF4E levels induced by 4EASO treatment is correlated with reduced cell viability, induced apoptosis, disrupted eIF4F complex formation, reduced expression of malignancy related proteins and enhanced chemosensitization of mesothelioma cells." (PMID 24260583, 2013). "In all mesothelioma cell lines, LY249002 treatment resulted in a decrease in the eIF4G/eIF4E ratio in IGF-I-stimulated cells than in cells treated with only IGF-I." (PMID 19603014, 2009). "In previous work it was shown that cap-mediated translation is enhanced in mesothelioma compared to normal mesothelial (LP9) cells and may be a consequence of Ras signaling pathway, phosphorylation of eIF4E and lower 4EBP1 levels." (PMID 24260583, 2013). "In mesothelioma, the primary mechanism for elevated levels of cap-mediated translation seems to be a low-level expression of the 4E-BP1 repressor protein in conjunction with an activation of eIF4E." (PMID 19603014, 2009). "4EASO potently diminished eIF4E protein levels, repressed cap-dependent complex formation, selectively reduced eIF4E regulated proteins (ODC and Bcl-2), reduced mesothelioma cell viability, induced apoptosis, and sensitized mesothelioma cells to gemcitabine and pemetrexed." (PMID 24260583, 2013).
neuroblastoma (4 papers, 2016 to 2025). Neuroblastoma (NB) is the most common solid, extracranial childhood tumor. "Higher expression of HIF-2α, AGO2, or eIF4E was observed in NB specimens with advanced international neuroblastoma staging system (INSS) stages or MYCN amplification." (PMID 27276678, 2016). "Therefore, in MYCN-amplified neuroblastoma, MLN8237 inhibits p4E-BP1, leading to loss of eIF4G:eIF4E complex-mediated MCL-1 protein translation." (PMID 26859456, 2016).
oral cancer (4 papers, 2017 to 2025). "Ribavirin monotherapy in oral cancers reduced phospho-eIF4E levels in 4/6 patients but provided limited therapeutic benefit, with the best outcomes being stable disease lasting up to ~7 months suggesting eIF4E inhibition may be best in combination." (PMID 40485569, 2025). "The effect rapamycin may induce oral cancer cell apoptosis directly by suppressing 4E-BP1 phosphorylation through mTORC1 and indirectly by inactivating eIF4E." (PMID 36185289, 2022).
renal cell carcinoma (4 papers, 2016 to 2024). "For instance, in renal cell carcinoma, fluvastatin inhibits the kinase p70S6Kα, accompanied by an increase in the expression of PDCD4 and the formation of the eIF4E-binding protein-eIF4E complex, inducing apoptosis." (PMID 38672098, 2024). "EIF4E overexpression can promote cell proliferation and invasion of renal cell carcinoma (RCC)." (PMID 36147333, 2022).
sarcoma (4 papers, 2016 to 2021). A usually aggressive malignant neoplasm of the soft tissue or bone. "Mirroring MNK1/2 silencing, ETC-168 treatment strongly blocks eIF4E phosphorylation and represses expression of sarcoma-driving onco-proteins including E2F1, FOXM1, and WEE1." (PMID 33564073, 2021). "Moreover, the inhibition of IS on the interaction between eIF4G and eIF4E was significantly reduced in 4E-BP1 knockdown sarcoma U2OS cells, suggesting that IS inhibited cap-dependent translation initiation through 4E-BP1." (PMID 27056897, 2016).
Sepsis (4 papers, 2014 to 2022). Sepsis is defined as life-threatening organ dysfunction caused by a dysregulated host response to infection. "Another study reported that sepsis also inhibited the association of eIF4E with eIF4G, but the phosphorylation of p70S6K, phosphorylation of 4EBP1, and dissociation of eIF4E from 4EBP1 were unaffected in rat gastrocnemius muscle perfused with insulin." (PMID 33148163, 2020). "Previously, sepsis has been implicated in the reduction of EIF4E phosphorylation." (PMID 34654440, 2021). "In this study, miR-499a-5p was able to regulate sepsis-induced cardiomyopathy by targeting EIF4E, a translation initiation factor involved in the mRNA–ribosome binding step of eukaryotic protein synthesis." (PMID 36012630, 2022). "Moreover, as total PDCD4 is rapidly degraded upon its release from eIF4A, the lack of a detectable change in total PDCD4 suggests an alteration in eIF4A helicase activity is an unlikely mechanism for the sepsis-induced reduction in protein synthesis in the presence of normal eIF4E•eIF4G binding." (PMID 24945486, 2014). "While sepsis decreased S6K1 phosphorylation in muscle from both WT and DKO mice, the sepsis-induced decrease in eIF4E•eIF4G binding seen in WT mice was absent in DKO mice." (PMID 24945486, 2014). "In contradistinction, there was no sepsis-induced decrease in the amount of active eIF4E•eIF4G complex in muscle from DKO mice, although global protein synthesis was decreased." (PMID 24945486, 2014). "While sepsis did not alter the total amount of the m7GTP cap binding protein, eIF4E, it markedly decreased its interaction with the scaffolding protein eIF4G in WT mice." (PMID 24945486, 2014). "Sepsis decreased the binding of eIF4G to eIF4E in WT mice; however, eIF4E•eIF4G binding was not altered in DKO mice under either basal or septic conditions." (PMID 24945486, 2014). "While sepsis did not alter the total amount of eIF4E in muscle (data not shown), the amount of eIF4G bound to eIF4E in WT male mice was reduced 55%." (PMID 24945486, 2014). "Our result presented with an increased mRNA expression of EIF4E in sepsis patients and LPS-induced AC16 cells, while the mRNA expression was decreased in LPS-treated AC16 cells after miR-499a-5p mimic treatment, thus validating EIF4E as the downstream target of miR-499a-5p." (PMID 34654440, 2021).
Cerebral ischemia (3 papers, 2021 to 2023). Restriction of arterial blood supply to the brain associated with insufficient oxygenation to support the metabolic requirements of the tissue. "In cellular stress conditions, as brain ischemia, translational repressors named eukaryotic initiation factor (eIF) 4E-binding proteins (4E-BPs) specifically bind to eIF4E and are critical in the translational control." (PMID 34638676, 2021). "Thus, while the specific inhibition of eIF4E by eIF4E-binding proteins (4E-BPs) is a well-known control mechanism of translation inhibition, including cerebral ischemia, the knowledge of eIF4G regulation is incomplete." (PMID 35163752, 2022).
endometrial cancer (3 papers, 2019 to 2025). Primary or metastatic malignant neoplasm involving the endometrium (mucous membrane that lines the endometrial cavity). "In endometrial carcinoma, miR-320a is downregulated, and its mimic prevents endometrial cancer cells from migrating and invading by specifically targeting eIF4E." (PMID 40630212, 2025). "Upon eIF4E elevation in endometrial carcinoma, TGFBR1 induced HEC-1A cells to undergo endothelial-to-mesenchymal transition (EMT)." (PMID 40630212, 2025). "We further investigated the expression patterns of peIF2α, eIF2α, eIF3c, eIF3h, eIF4e, eIF4g, eIF5 and eIF6 in endometrial cancer compared to non-neoplastic patient samples using immunoblot analysis." (PMID 31817792, 2019).
hepatitis C (3 papers, 2018 to 2025). "Ribavirin, that target the eIF4E translation initiation factor, is used to treat hepatitis C, and is under investigation for recurrent or metastatic OPSCC (ClinicalTrials.gov, NCT02308241)." (PMID 29879932, 2018). "Nine of these studies involve agents targeting eIF4E, being either ribavirin, an agent initially developed against hepatitis C, ISIS EIF4E Rx, an antisense oligonucleotide against eIF4E, or LY2275796, another antisense oligonucleotide blocking the expression of eIF4E." (PMID 32726992, 2020).
invasive carcinoma (3 papers, 2006 to 2021). A carcinoma that is not confined to the epithelium, and has spread to the surrounding stroma. "We also found that phospho-eIF4E levels increased significantly, from normal urothelium to invasive carcinoma in vivo." (PMID 34032633, 2021). "An increased level of eIF4E gene amplification was observed when benign tumors and invasive carcinomas of the head and neck were compared." (PMID 20049173, 2009). "In addition, we found that invasive carcinoma was different from non-invasive carcinoma with respect to eIF4E immunostaining (p = 0.034)." (PMID 17010208, 2006).
ischemia (3 papers, 2015 to 2023). A hypoperfusion of the BLOOD through an organ or tissue caused by a PATHOLOGIC CONSTRICTION or obstruction of its BLOOD VESSELS, or an absence of BLOOD CIRCULATION. "Therefore, we can conclude an association between DRP2–4E-BP2–eIF4E in the vulnerable CA1 region after ischemia reperfusion that would reduce the availability of “active” eIF4E (unbound to 4E-BP2), essential to protein synthesis, an association that would be dependent on DRP2 phosphorylation." (PMID 37175950, 2023). "The differential DRP2 isoforms in brain tissue reported here are certainly findings that require further studies in order to confirm the DRP2-phosphorylation-dependent mechanism involved in the regulation of 4E-BP2 and eIF4E in ischemia reperfusion." (PMID 37175950, 2023). "We study if eIF4E –the other partner in 4E-BP2/eIF4E association—was implicated in ischemia and IR stress, or correlated with 4E-BP2/eIF4E association." (PMID 25822952, 2015).
lung squamous cell carcinoma (3 papers, 2016 to 2022). "The overexpression percentage of p-4EBP1 and p-eIF4E in lung squamous cell carcinoma (SCC) and adenocarcinoma (ADC) was significantly higher than that of Non-CLT." (PMID 35737644, 2022).